Y_RNA (Y RNA )
Gene: Miscellaneous RNA gene on chromosome 17 (60,748,940 to 60,749,046, reverse strand). Ensembl gene ENSG00000252534.
Homologues: Orthologues: chimpanzee Y_RNA (99% identical), macaque Y_RNA (96% identical), guinea pig Y_RNA (88% identical), dog Y_RNA (81% identical). Paralogues in human: RNY1 (93% identical), Y_RNA (88% identical), Y_RNA (87% identical), Y_RNA (86% identical), RNY1P11 (85% identical), Y_RNA (85% identical), Y_RNA (84% identical), RNY1P8 (83% identical), Y_RNA (83% identical), RNY1P10 (82% identical), Y_RNA (82% identical), Y_RNA (81% identical), and 98 more.